LIPF (lipase F, gastric type)
Description:
Catalyzes the hydrolysis of triacylglycerols to yield free fatty acids, diacylglycerol, monoacylglycerol, and glycerol. Shows a preferential hydrolysis at the sn-3 position of triacylglycerol.
Synonyms: GL; HGL; HLAL
Tractability: Small molecule: an approved drug acts on it; it has a high-quality binding pocket; it belongs to a druggable protein family. Antibody: UniProt places it where antibodies can reach, with medium confidence; UniProt predicts a signal peptide or a membrane-spanning region; its Gene Ontology location is reachable by antibodies, with medium confidence.
Target class: Enzyme; Hydrolase
Gene: Protein-coding gene on chromosome 10 (88,664,441 to 88,678,814, forward strand). Ensembl gene ENSG00000182333.
Subcellular location: Secreted
Pathways (Reactome):
Digestion and absorption: Digestion of dietary lipid
Gene Ontology:
Molecular function: protein binding; triacylglycerol lipase activity; lipid binding; carboxylic ester hydrolase activity; hydrolase activity, acting on ester bonds; lipase activity; malate dehydrogenase activity
Biological process: lipid metabolic process; triglyceride metabolic process
Cellular component: extracellular region; mitochondrion
Genetic constraint (gnomAD): Loss-of-function variants: 9 observed, 13.81 expected, observed/expected ratio (o/e) 0.65, 90% interval 0.39 to 1.14. The upper end of that interval is the gene's LOEUF score, 1.14, which puts it in group 4 of 6, group 1 being the genes least tolerant of losing a copy. Missense variants: 202 observed, 230.38 expected, observed/expected ratio (o/e) 0.88, 90% interval 0.78 to 0.99. Synonymous variants: 77 observed, 83.03 expected, observed/expected ratio (o/e) 0.93, 90% interval 0.77 to 1.12.
Homologues: Orthologues: chimpanzee LIPF (99% identical), macaque LIPF (93% identical), dog LIPF (85% identical), rabbit LIPF (84% identical), guinea pig LIPF (80% identical), mouse Lipf (77% identical), rat Lipf (76% identical), Caenorhabditis elegans lipl-2 (42% identical), Caenorhabditis elegans lipl-3 (41% identical), Caenorhabditis elegans lipl-1 (41% identical), Caenorhabditis elegans lipl-5 (41% identical), Caenorhabditis elegans lipl-6 (40% identical), and 23 more. Paralogues in human: LIPK (63% identical), LIPA (57% identical), LIPJ (53% identical), LIPM (52% identical), LIPN (51% identical).
Diseases named in the same sentence as LIPF in open-access papers:
LIPF is named in the same sentence as 23 diseases in open-access papers, as found by Europe PMC text mining. Sharing a sentence is not in itself a finding about the gene and the disease. The quoted sentences say what the papers report.
gastric cancer (7 papers, 2021 to 2024). A primary or metastatic malignant neoplasm involving the stomach. "Interestingly, we and others have previously identified LIPF as a lineage-specific target of recurrent insertion–deletion mutations in gastric cancer." (PMID 34642171, 2022). "Similarly, LIPF encodes gastric lipase F, a critical triglyceride metabolic enzyme secreted mainly by chief cells in the gastric fundus, the repression of which is associated with gastric cancer." (PMID 39300663, 2024). "The connection between LIPC and LIPF, known for its involvement in lipid metabolic processes and downregulation in gastric cancer, added another layer of complexity to the potential role of LIPC in HNSCC." (PMID 38192945, 2023). "Among most downregulated genes we found GPX3, PTGER3 and LIPF (−47.5 and −435.63 of fold change for Diffuse and Intestinal tumors respectively), that resulted hypermethylated in gastric cancer." (PMID 34012923, 2021). "Gastric lipase (LIPF) is highly expressed in the normal stomach and showed significantly low expression in gastric adenocarcinoma, suggesting that it can be used as a diagnostic and prognostic indicator for gastric cancer." (PMID 33885377, 2021). "For example, a lower expression of genes that may play an important role in suppressing gastric cancer (GKN1, LIPF, ANXA10, MUC6, PSCA, and SNHG5) was found." (PMID 35625760, 2022).
Obesity (6 papers, 2013 to 2025). Accumulation of substantial excess body fat. "Among the target genes with the highest absolute CAP score difference are VWF (which is targeted by antihemophilic factor), SIRT5 (targeted by suramin for treating sleeping sickness), and the gastric lipase LIPF (targeted by orlistat for obesity treatment)." (PMID 29273096, 2017).
gastric adenocarcinoma (2 papers, 2021 to 2025). "Conversely, the most significantly downregulated genes included LIPF (gastric lipase), PGA4 and PGA3 (pepsinogens), reflecting the characteristic loss of gastric digestive enzyme production in gastric adenocarcinoma." (PMID 40725485, 2025).
breast carcinoma (1 paper, 2022). "Also, LIPF and MUC19, the gene that expresses SMGC, was associated with a worse survival probability in patients with breast cancer." (PMID 35798767, 2022).
prostate carcinoma (1 paper, 2020). A carcinoma that arises from epithelial cells of the prostate gland. "In addition to the uptake of extracellular free fatty acid through LIPF and CD36, our model also suggested that prostate cancer cells also exhibit elevated de novo fatty acid synthesis." (PMID 32103057, 2020).
cancer (5 papers, 2011 to 2025). A tumor composed of atypical neoplastic, often pleomorphic cells that invade other tissues. "The center of the cancer (III) demonstrates high expression of LIPF, which can generate free fatty acids for cancer cells to uptake." (PMID 40033360, 2025). "Our modeling analysis suggests that Lipase F (LIPF) can potentially degrade extracellular triglycerides and generate free fatty acids for cancer cells to uptake." (PMID 32103057, 2020). "A similar phenomenon was observed with genes such as KRT4, LIPF, TG, and PGC, which are also almost exclusively expressed in specific tissues, making them less suitable for pan-cancer classification." (PMID 39118043, 2024).
tumor (4 papers, 2021 to 2022). "GTL is a protein expressed by the LIPF gene and contributes to the metabolism of adipose tissue, favoring a catabolic state that assists the proliferation of tumor cells." (PMID 35798767, 2022). "Among downregulated genes, the classic chief cell markers LIPF and PGA3 were among the top downregulated genes in tumor epithelial cells (P < 0.0001)." (PMID 34642171, 2022).
LIPF also shares sentences with these, for which no sentence is quoted: hyperthyroidism (2 papers); acute pancreatitis (1); anorexia nervosa (1); Arrhythmia (1); atherosclerosis (1); chronic atrophic gastritis (1); exocrine pancreatic insufficiency (1); gastroesophageal reflux (1); hypertriglyceridemia (1); Intestinal tumors (1); pancreatic disease (1); primary biliary cholangitis (1); psoriasis (1); rheumatoid arthritis (1); sleeping sickness (1); systemic lupus erythematosus (1).